NTSR1 (neurotensin receptor 1)
Description:
G protein-coupled receptor for the tridecapeptide neurotensin (NTS). Signaling is effected via G proteins that activate a phosphatidylinositol-calcium second messenger system. Signaling leads to the activation of downstream MAP kinases and protects cells against apoptosis.
Synonyms: NTR
Tractability: Small molecule: a drug acting on it is in phase 2 or 3 trials; a structure with a bound ligand is known; a high-quality ligand is known; it belongs to a druggable protein family. Antibody: UniProt places it where antibodies can reach, with high confidence; its Gene Ontology location is reachable by antibodies, with high confidence; UniProt predicts a signal peptide or a membrane-spanning region; the Human Protein Atlas places it where antibodies can reach. PROTAC: ubiquitination databases record sites on it; its protein half-life has been measured; a small molecule that binds it is known.
Target class: Family A G protein-coupled receptor; Peptide receptor (family A GPCR); Membrane receptor; Short peptide receptor (family A GPCR); Neurotensin receptor
Chemical probes: ML301, ML314, meclinertant (high quality)
Gene: Protein-coding gene on chromosome 20 (62,708,836 to 62,762,771, forward strand). Ensembl gene ENSG00000101188.
Subcellular location: Cell membrane; Membrane raft
Subcellular location (Human Protein Atlas): Plasma membrane
Pathways (Reactome):
Signal Transduction: G alpha (q) signalling events; Peptide ligand-binding receptors
Gene Ontology:
Molecular function: G protein-coupled neurotensin receptor activity; identical protein binding; protein binding; G protein-coupled receptor activity; protein-containing complex binding
Biological process: negative regulation of apoptotic process; neuropeptide signaling pathway; positive regulation of gene expression; chemical synaptic transmission; G protein-coupled receptor signaling pathway; associative learning; cAMP biosynthetic process; conditioned place preference; D-aspartate import across plasma membrane; detection of temperature stimulus involved in sensory perception of pain; inositol phosphate catabolic process; L-glutamate import across plasma membrane; learning; negative regulation of release of sequestered calcium ion into cytosol; negative regulation of systemic arterial blood pressure; positive regulation of apoptotic process; positive regulation of arachidonate secretion; positive regulation of gamma-aminobutyric acid secretion; positive regulation of glutamate secretion; positive regulation of inhibitory postsynaptic potential; positive regulation of inositol phosphate biosynthetic process; positive regulation of locomotion; positive regulation of release of sequestered calcium ion into cytosol; regulation of behavioral fear response; regulation of inositol trisphosphate biosynthetic process; and 7 more
Cellular component: membrane raft; plasma membrane; endoplasmic reticulum; Golgi apparatus; axon; axon terminus; cell surface; cytoplasmic side of plasma membrane; dendrite; dendritic shaft; dendritic spine; membrane; neuron spine; neuronal cell body; perikaryon; symmetric synapse; terminal bouton
Genetic constraint (gnomAD): Loss-of-function variants: 29 observed, 31.34 expected, observed/expected ratio (o/e) 0.93, 90% interval 0.69 to 1.26. The upper end of that interval is the gene's LOEUF score, 1.26, which puts it in group 5 of 6, group 1 being the genes least tolerant of losing a copy. Missense variants: 697 observed, 603.51 expected, observed/expected ratio (o/e) 1.15, 90% interval 1.09 to 1.23. Synonymous variants: 282 observed, 276.76 expected, observed/expected ratio (o/e) 1.02, 90% interval 0.92 to 1.12.
Homologues: Orthologues: macaque NTSR1 (99% identical), guinea pig NTSR1 (88% identical), dog NTSR1 (86% identical), mouse Ntsr1 (85% identical), rat Ntsr1 (85% identical), pig NTSR1 (84% identical), chimpanzee NTSR1 (83% identical), tropical clawed frog NTSR1 (57% identical), zebrafish ntsr1 (56% identical). Paralogues in human: NTSR2 (35% identical), MLNR (31% identical), GHSR (27% identical), NMUR2 (27% identical), GPR39 (26% identical), NMUR1 (26% identical), TRHR (21% identical), EDNRA (20% identical), GRPR (20% identical), EDNRB (20% identical), BRS3 (19% identical), NMBR (19% identical), and 3 more.
Diseases named in the same sentence as NTSR1 in open-access papers:
NTSR1 is named in the same sentence as 89 diseases in open-access papers, as found by Europe PMC text mining. Sharing a sentence is not in itself a finding about the gene and the disease. The quoted sentences say what the papers report.
pancreatic cancer (16 papers, 2011 to 2024). "Autoradio-radiographic studies have shown that the density of type 2 somatostatin receptors in NETs can reach the level of NTSR1 in pancreatic cancer." (PMID 38496894, 2024). "OAd/DCN/LRP-PEG-NT effectively targeted neurotensin receptor 1 (NTR)-overexpressing pancreatic cancer cells." (PMID 39337402, 2024). "As expected, many differential SE-associated genes in PSN1 were the key genes of pancreatic cancer, such as S100A4, S100A6, S100A2, NTSR1 and CDK5." (PMID 36318264, 2023). "The overexpression of NTSR1 induced high tumorigenic and metastatic capacity in pancreatic cancer cells." (PMID 36318264, 2023). "Neurotensin receptor 1 has been found to be overexpressed in various cancers such as colorectal, small cell and non-small cell bronchial, breast and pancreatic cancer." (PMID 34976584, 2022). "According to the Cancer Cell Line Encyclopedia (CCLE), the mRNA expression level of NTSR1 was high in pancreatic cancer cell lines compared with other tumor cell lines." (PMID 33034134, 2021). "Although further studies are needed, our findings suggest that NTS/NTSR1 signaling contributes to the acquisition of a malignant phenotype by pancreatic cancer cells through the induction of EMT and inflammation." (PMID 33034134, 2021). "The functional role of NTSR1 in pancreatic cancer progression was examined in vivo using NTSR1‐overexpressing cells." (PMID 33034134, 2021). "Then, we tried to identify important genes for pancreatic cancer progression among target(s) for NTS/NTSR1 signaling." (PMID 33034134, 2021). "In the present study, we identified the NTS/NTSR1 target genes in pancreatic cancer cells by a genome‐wide RNA‐seq analysis." (PMID 33034134, 2021). "Several reports showed that NTS/NTSR1 signaling is involved in the progression of pancreatic cancer." (PMID 33034134, 2021). "Our results thus validated proof of concept for NTS/NTSR1‐targeting strategy in pancreatic cancer treatment." (PMID 33034134, 2021). "Neurotensin (NTS) receptor 1 (NTSR1) is expressed in highly malignant pancreatic cancer cells, which were established by serial orthotopic transplantations." (PMID 33034134, 2021). "Overexpression of NTSR1 in human pancreatic cancer cells Panc‐1 and SUIT‐2 accelerated their tumorigenic and metastatic abilities in vivo." (PMID 33034134, 2021). "Taken together, these findings prompted us to explore the biological function of NTSR1 in pancreatic cancer using mouse models and to identify the target genes of NTS/NTSR1 signaling pathway using genome‐wide gene expression analysis." (PMID 33034134, 2021). "Based on our previous RNA‐sequence analysis, we found increased expression levels of neurotensin (NTS) receptor 1 (NTSR1) in highly malignant pancreatic cancer sublines." (PMID 33034134, 2021). "NTS/NTSR1 signaling contributes to the progression of pancreatic cancer through the activation of MAPK and NF‐κB signaling pathways and the induction of the genes related to inflammation." (PMID 33034134, 2021). "We showed that NTSR1 is specifically expressed in highly malignant pancreatic cancer sublines, which was also observed in clinical datasets of pancreatic cancers." (PMID 33034134, 2021). "The intensity of NTSR1 increases with the stage of pancreatic cancer and metastases express NTSR1 at the same level as the primary tumour." (PMID 32336282, 2020). "The enhanced release of IL-8 induced by NTS/NTSR1 has been confirmed in pancreatic cancer, hepatocellular carcinomas and colon cancer." (PMID 25644759, 2015). "Meanwhile, NTSR1 is also considered to be closely related to pancreatic cancer." (PMID 36318264, 2023). "In addition to MMP‐9, various kinds of secreted proteins were identified as targets for NTS/NTSR1 in pancreatic cancers." (PMID 33034134, 2021). "In addition, overexpression of NTSR1 in pancreatic cancer cells resulted in enhanced primary tumor formation and metastasis in vivo." (PMID 33034134, 2021).
pancreatic cancer (continued). "In addition, a re‐analysis of the TCGA database on pancreatic cancer showed that the expression of NTSR1 mRNA was particularly increased in patients with advanced stages of pancreatic cancer." (PMID 33034134, 2021). "Targeting NTSR1 signaling by SR48692 inhibits pancreatic cancer progression." (PMID 33034134, 2021). "Next, we examined the clinical significance of NTSR1 expression in pancreatic cancers." (PMID 33034134, 2021). "Furthermore, re‐analysis of clinical databases revealed that the expression level of NTSR1 was increased in advanced pancreatic cancer and that high NTSR1 levels were correlated with a poor prognosis." (PMID 33034134, 2021). "Neurotensin receptor 1 (NTSR1) can combine with neurotensin (NTS) to form a complex to promote tumor progression in solid tumors such as prostate cancer, colorectal cancer, and pancreatic cancer." (PMID 35251577, 2022). "Next, we analyzed the effects of a small molecular weight NTSR1 antagonist, SR48692, on pancreatic cancer progression." (PMID 33034134, 2021). "Overexpression of NTSR1 in pancreatic cancer cells promoted tumorigenicity and metastatic ability in vivo, suggesting a pro‐tumorigenic role for NTS/NTSR1 signaling." (PMID 33034134, 2021). "Previous researches also confirmed that the effect of NTS/NTSR1 stimulation on cell growth mainly mediated by MEK/ERK1/2 phosphorylation pathway in colon cancer and pancreatic cancer." (PMID 25644759, 2015). "We clearly demonstrated that highly malignant pancreatic cancer cells express NTSR1, not NTSR2 and SORT1, as a receptor for NTS." (PMID 33034134, 2021). "We identified target(s) for NTS/NTSR signaling in pancreatic cancer cells and also aimed to determine whether NTS/NTSR1 signaling pathways might be potential target(s) for pancreatic cancer treatment in vivo." (PMID 33034134, 2021). "Furthermore, the neurotensin receptor 1 (NTSR1) was found to be overexpressed in breast, prostate, colorectal, lung, liver, and pancreas cancers among others." (PMID 32733853, 2020). "Neither the parental cells nor the established pancreatic cancer sublines expressed NTS, suggesting that the endogenous NTS/NTSR1 signaling was not activated, at least in an autocrine manner." (PMID 33034134, 2021).
prostate carcinoma (16 papers, 2009 to 2026). A carcinoma that arises from epithelial cells of the prostate gland. "NT, binding to NTSR1, causes prostatic cancer cell mitosis through Src-, MMP- and PKC-dependent transactivation of EGFR, which ultimately stimulate the MAP-kinase pathway in a PI3K-dependent manner." (PMID 32336282, 2020). "High NTSR1 expression results in poor prognosis of patients with ductal breast cancer, prostate cancer, or head and neck squamous carcinoma." (PMID 37508387, 2023). "New targets for prostate cancer are currently being studied, such as neurotensin receptor-1 (NTS1), somatostatin receptor-2 (SST2) or chemokine receptor-4 (CXCR4) —suggested to be expressed in prostate cancer in a few small pilot studies." (PMID 37190273, 2023). "A recent study identified downstream NTS/NTSR1 targets which were important for neuroendocrine differentiation of CK8+/CK14+ prostate cancer cells." (PMID 33034134, 2021). "Other groups have shown that NTSR1 is a high potential target ligand in imaging and therapy for colonic, pancreatic and prostatic cancers." (PMID 32764278, 2020). "The tumour growth over 57 days and survival was significantly different between the treatment and control group, showing that NTSR1 could be a suitable molecular target in PSMA-negative prostate carcinoma for radiotherapy." (PMID 32336282, 2020). "In addition, it has been showed that NTSR1 induces and enhances the invasive phenotype in prostate cancer cells (LNCaP) and HNSCC tumor cells." (PMID 25249545, 2014). "For example, NTSR1 (Neurotensin Receptor 1) has been reported as a potential prognostic biomarker for surgically resected stage I LUAD and prostate cancer." (PMID 33195688, 2020). "Neurotensin receptor 1 (NTS1) is overexpressed on a variety of cancer entities; for example, prostate cancer, ductal pancreatic adenocarcinoma, and breast cancer." (PMID 28287433, 2017). "Moreover, NTSR1 blockade with the selective NTSR1 antagonist, SR48692, inhibits Neurotensin-mediated prostatic cancer growth." (PMID 32336282, 2020). "More recently, it was shown that NTSR1 activation results in EGFR transactivation by the shedding of transforming growth factor-α (TGF-α) in pancreas, and HB-EGF or amphiregulin in prostate cancer cells, both leading to ERK1/2 activation, but also EGFR expression." (PMID 19156213, 2009). "NTS was acutely induced by androgen deprivation in animal models of prostate cancer (PCa) and activated downstream signaling leading to NED through activation of neurotensin receptor 1 (NTSR1) and neurotensin receptor 3 (NTSR3), but not neurotensin receptor 2 (NTSR2)." (PMID 30770901, 2019).
lung carcinoma (15 papers, 2009 to 2026). "The removal of NTSR1 expression in both lung and breast cancer cells caused a reduction of tumor growth and metastasis, demonstrating the contribution of this complex in tumor progression in breast and lung cancers." (PMID 25249545, 2014). "NTS and NTSR1 are implicated in several detrimental functions linked to the neoplastic progression, including proliferation of the pancreas, prostate, colon and lung cancer cells, protection of breast cancer cells against apoptosis, and induction of the proinvasive potential of colon cancer cells." (PMID 19156213, 2009). "Meanwhile, NTSR1 was over‐expressed in LUAD84 and proved to be linked to the lung cancer's progression." (PMID 38013642, 2024). "Previous studies support our finding that NTSR1-overexpression enhances lung cancer cell migration and invasion, increases FAK and paxillin phosphorylation, and affects F-actin distribution." (PMID 37726723, 2023). "SLCO4A1-AS1 reverses TOX4/NTSR1-dependent migration and invasion and reduces lung cancer cell motility by remodeling the cytoskeleton." (PMID 37726723, 2023). "In this study, we have discovered that TOX4 directly binds to the NTSR1 promoter and enhances transcription of the NTSR1 gene in lung cancer cells." (PMID 37726723, 2023). "Lung cancer patients with high NTSR1 have decreased relapse-free survival than patients with low NTSR1." (PMID 37508387, 2023). "High expression of NTS and its receptor NTSR1 are identified in lung cancer, compared with normal cells." (PMID 32121246, 2020). "The expression pattern of GHSR1b and NTSR1 was significantly correlated with the NMU expression pattern in the examined lung cancer tissue samples." (PMID 31492042, 2019). "S-acylation of the neurotensin receptor 1 (NTSR-1), a key mediator in breast, pancreas, prostate, colon and lung cancers, is essential for its localization and efficient signaling." (PMID 28392791, 2017). "Methylation of NTSR1 has been reported in pancreatic and lung cancers, suggesting NTSR1 is a methylation-prone gene in tumors of multiple organs." (PMID 26334593, 2015). "Here we highlight the cellular mechanisms activated by Neurotensin (NTS) and its high affinity receptor (NTSR1) contributing to lung cancer cell aggressiveness." (PMID 25249545, 2014). "In human tumors, both NTS and NTSR1 are expressed in 40%, 60%, 65%, and 80 % of breast and lung cancers, mesotheliomas, and head and neck squamous cell carcinomas, respectively, suggesting that autocrine and/or paracrine NTS regulation occurs in tumors." (PMID 25249545, 2014). "The only other NMU receptor reported in the literature is a heterodimer of the neurotensin receptor 1 (NTSR1) and the growth hormone secretagogue receptor 1 b, identified in human lung cancer cells." (PMID 22314006, 2012). "In fact, there is only isolated evidence that GHSR1b can act as a co-receptor with the neurotensin receptor 1 to form a novel receptor for neuromedin U in lung cancer." (PMID 21829727, 2011). "The regulatory network of SLCO4A1-AS1, TOX4, and NTSR1 in regulating cancer migration and invasion may provide potential anti-metastatic therapeutic targets for the treatment of lung cancer." (PMID 37726723, 2023). "Higher expression of NTS and NTSR1 has been observed in lung cancer tissues than in normal tissues." (PMID 37726723, 2023). "Consequently, this leads to a reduction in NTSR1 expression, ultimately inhibiting lung cancer migration and invasion." (PMID 37726723, 2023). "Interestingly, in animal and cell models for NTS-expressing lung cancers, treatment with an NTSR1 antagonists resulted in increased cytotoxicity of anti-EGFR chemotherapy." (PMID 31489118, 2019). "We have focused on the contribution of NTS/NTSR1 complex in breast and lung cancers." (PMID 25249545, 2014). "Neurotensin (NTS) and its high affinity receptor (NTSR1) are up regulated in 60% of lung cancers." (PMID 25249545, 2014).
lung carcinoma (continued). "The results indicate that NTSR1 regulates HER4 transactivation, thereby increasing the proliferation of lung cancer cells." (PMID 42117825, 2026). "In summary, SLCO4A1-AS1 exerts its inhibitory influence on NTSR1 expression through its interaction with TOX4, thereby exerting a modulatory control over the migratory and invasive behaviors of lung cancer cells." (PMID 37726723, 2023). "The evidence showed that NTSR1 is a novel and convergent downstream target of SLCO4A1-AS1/TOX4 and is involved in regulating SLCO4A1-AS1/TOX4-mediated migration and invasion in lung cancer cells." (PMID 37726723, 2023). "Adding neurotensin to lung cancer cells increases phosphatidylinositol turnover, resulting in elevating cytosolic Ca2+ and activating protein kinase C. SR48692 is an NTSR1 antagonist, which inhibits lung cancer proliferation." (PMID 37508387, 2023). "The pharmacological effect of inhibition of NTSR1 signaling using siRNAs or SR48692 has been already estimated in a wide variety of cancers, such as lung cancer, colon cancer, ovarian cancer, melanoma, and glioma." (PMID 33034134, 2021). "miR-939 regulates a large number of genes, such as WNT1, NTSR1, POLK, WWOX and SPN, that are related to lung cancer." (PMID 29228624, 2017). "By Western blot, NTSR1 and HER4 were present in six lung cancer cell lines examined." (PMID 42117825, 2026). "Lung cancer proliferation is impaired by SR48692, an NTSR1 antagonist." (PMID 37508387, 2023). "NTSR1 mRNA is present in lung cancer cells but not NTSR2 mRNA." (PMID 37508387, 2023). "The heterodimer NTSR1/GHSR1b, which was found to pass down the NMU signal in lung cancer cells, intensified the production of cAMP but not intracellular calcium mobilization." (PMID 31492042, 2019).